BTLA (B and T lymphocyte associated)
Description:
Inhibitory receptor on lymphocytes that negatively regulates antigen receptor signaling via PTPN6/SHP-1 and PTPN11/SHP-2. May interact in cis (on the same cell) or in trans (on other cells) with TNFRSF14. In cis interactions, appears to play an immune regulatory role inhibiting in trans interactions in naive T cells to maintain a resting state. In trans interactions, can predominate during adaptive immune response to provide survival signals to effector T cells.
Synonyms: CD272; BTLA1
Tractability: Small molecule: a structure with a bound ligand is known. Antibody: UniProt places it where antibodies can reach, with high confidence; its Gene Ontology location is reachable by antibodies, with high confidence; UniProt predicts a signal peptide or a membrane-spanning region. PROTAC: its protein half-life has been measured.
Gene: Protein-coding gene on chromosome 3 (112,461,067 to 112,499,668, reverse strand). Ensembl gene ENSG00000186265.
Subcellular location: Cell membrane
Pathways (Reactome):
Immune System: Co-inhibition by BTLA
Gene Ontology:
Molecular function: protein binding; signaling receptor activity
Biological process: negative regulation of T cell proliferation; regulation of ERK1 and ERK2 cascade; regulation of T cell tolerance induction to tumor cell; immune response-regulating cell surface receptor signaling pathway; negative regulation of T cell activation; negative regulation of T cell cytokine production; regulation of B cell proliferation; regulation of immune response
Cellular component: plasma membrane; plasma membrane protein complex
Genetic constraint (gnomAD): Loss-of-function variants: 9 observed, 20.44 expected, observed/expected ratio (o/e) 0.44, 90% interval 0.26 to 0.77. The upper end of that interval is the gene's LOEUF score, 0.77, which puts it in group 3 of 6, group 1 being the genes least tolerant of losing a copy. Missense variants: 253 observed, 310.01 expected, observed/expected ratio (o/e) 0.82, 90% interval 0.74 to 0.91. Synonymous variants: 92 observed, 112.39 expected, observed/expected ratio (o/e) 0.82, 90% interval 0.69 to 0.97.
Homologues: Orthologues: chimpanzee BTLA (99% identical), macaque BTLA (89% identical), dog BTLA (65% identical), guinea pig BTLA (64% identical), mouse Btla (55% identical), rat Btla (50% identical).
Diseases named in the same sentence as BTLA in open-access papers:
BTLA is named in the same sentence as 165 diseases in open-access papers, as found by Europe PMC text mining. Sharing a sentence is not in itself a finding about the gene and the disease. The quoted sentences say what the papers report.
melanoma (59 papers, 2013 to 2025). A malignant, usually aggressive tumor composed of atypical, neoplastic melanocytes. "In melanoma, increased BTLA levels have been linked to disease relapse and poor response to PD-1 blockade." (PMID 41471273, 2025). "Elevated levels of BTLA in melanoma have been previously associated with increased immune filtration levels (namely CD8+ T cells) and improved prognosis." (PMID 39796775, 2025). "BTLA expression on TIL in adaptive cell therapy for melanoma is associated with a better response to treatment." (PMID 36140182, 2022). "It has been shown that tumor-specific T cells in melanoma patients express high levels of BTLA, and that immunotherapies associated with BTLA-downregulation can improve T cell responses." (PMID 36081508, 2022). "In summary, our study demonstrates that upregulated BTLA is associated with longer clinical survival, higher immune infiltration levels, and better immunotherapeutic benefit in melanoma patients." (PMID 33718105, 2020). "In contrast, human melanoma Ag-specific effector CD8+ T cells persistently express high levels of BTLA and remain susceptible to the functional inhibition mediated by its ligand HVEM." (PMID 28404974, 2017). "BTLA overexpression has been reported in hematological malignancies and melanoma and appears to be associated with impaired tumor-specific T-cell activity, particularly with PD-1 expression." (PMID 27283895, 2016). "Recently, a positive association of CD8+ T cells expressing BTLA with clinical response to adoptive T cell therapy in late-stage melanoma patients has been suggested by Haymaker." (PMID 24782858, 2014). "Next, we analyzed whether the metastatic status was associated with the survival outcomes of BTLA expression level in melanoma." (PMID 33718105, 2020). "Furthermore BTLA expression on CD8+ tumor-infiltrating lymphocytes was associated with improved clinical outcome in melanoma, aligning with our observation that SLAMF7 co-stimulation supports a less-differentiated, cytotoxic phenotype with sustained effector capacity." (PMID 40909279, 2025). "Elevated BTLA expression in tumor-infiltrating lymphocytes correlates with poor prognosis in several cancers, including non-small-cell lung, hepatocellular, melanoma, and gastric carcinomas." (PMID 41471273, 2025). "For example, the expression of BTLA is upregulated in gallbladder cancer and elevated in the T-cells of patients with melanoma and lung cancer." (PMID 39312339, 2024). "The presence of anti-BTLA Abs alone or in combination with other blocking Abs decreased melanoma cell numbers and increased the T-cell to melanoma cell ratio." (PMID 38233898, 2024). "The simultaneous application of an anti-BTLA antibody led to an increase of the T-cell/melanoma cell ratio indicating an immune activating and anti-tumoral activity of BTLA inhibition." (PMID 38928307, 2024). "BTLA mRNA expression was found to be higher in metastatic patients than in patients with primary melanoma and HC." (PMID 38233898, 2024). "The overexpression of BTLA was also observed in patients with melanoma, gallbladder cancer, diffuse large-B cell lymphoma, clear cell renal cell cancer, and prostate cancer." (PMID 38835768, 2024). "Similar results have been detected on T cell subsets in other types of cancer, such as BTLA upregulation on peripheral CD4 + T cells in hepatocellular carcinoma or tumor antigen-specific CD8 + T cells from melanoma." (PMID 37041226, 2023). "As an example, BTLA is overexpressed in CD8+ T lymphocytes specific for the tumor antigen NY-ESO-1 in melanoma." (PMID 37649037, 2023). "More specifically, tumor antigen-specific CD8 + T cells displayed enhanced cytokine production and proliferation upon BTLA blockade in melanoma models in vitro." (PMID 37041226, 2023). "Of note, GIMAP7 mRNA expression displays impressive correlations with immune checkpoints PDL2, CD96, TIGIT, BTLA, other immune checkpoints in melanoma, and across 30 cancer types." (PMID 36588164, 2023).
melanoma (continued). "Multispectral immunofluorescence assays revealed that BTLA+ CD8+ T cells were physically related to HVEM+ tumor cells, thereby suggesting that HVEM molecules on melanoma cells inhibit infiltrating T cells via BTLA." (PMID 37649037, 2023). "In the blockade of BTLA, an increase in the proliferation and expansion of NY-ESO-1-specific CD8+ T-cells was observed, and an increased efficiency of the use of antibodies targeting BTLA in combination with anti-PD-1 and anti-Tim-3 in melanoma was shown." (PMID 36140182, 2022). "In melanoma, where BTLA is highly expressed on tumor-specific CD8+ T cells, its blockade resulted in enhanced proliferation and cytokine production." (PMID 36741370, 2022). "Preclinical evaluations in melanoma evidence the promising activity of monoclonal anti-BTLA antibodies by leading the promotion of T cell immune response." (PMID 34371708, 2021). "◾ BTLA expression increases in patients with GBC, HCC, DLBCL, and melanoma, and is associated with poor prognosis." (PMID 33859648, 2021). "The present study aimed to reveal the expression pattern and potential prognostic and immunotherapeutic value of BTLA in melanoma." (PMID 33718105, 2020). "The potential clinical significance of these findings is underscored by in vitro observations that HVEM‐expressing melanoma cell lines inhibit IFN‐γ production by Melan‐AMART‐1 Ag‐specific CD8+ T cell clones in a BTLA‐dependent manner." (PMID 32508018, 2020). "We found that BTLA levels were upregulated in metastatic melanoma compared to normal skin tissues and primary melanoma." (PMID 33718105, 2020). "Tumor cells exploit this pathway by either promoting the formation of dysfunctional T cells that persistently express BTLA and render them susceptible to inactivation, or by expressing HVEM, as it has been found with melanoma." (PMID 29544515, 2018). "Preclinical results demonstrate that monoclonal anti-BTLA antibodies can promote T cell activation in melanoma patients by preventing BTLA/HVEM coinhibitory signaling, although safety profiles have yet to be established." (PMID 29725606, 2018). "In melanoma patients, BTLA was demonstrated to be expressed on tumor-specific T cells both in circulation and in metastatic lymph nodes." (PMID 29211042, 2017). "Such persistence of BTLA expression has also been found in tumor Ag-specific CD8+ T cells isolated from melanoma patients with spontaneous anti-tumor immune responses and after peptide vaccination." (PMID 28404974, 2017). "Prior studies demonstrated that this subset, CD8+BTLA+ T cells, possess a high proliferative capacity, generate their own IL-2 and display enhanced persistence in melanoma patients after TIL ACT." (PMID 27057427, 2016). "Fourcade and colleagues tested the significance of this expression, showing that BTLA blockade enhanced the proliferation and antitumor activity of melanoma-specific CD8+ T cells." (PMID 24855562, 2014). "For example, in patients with melanoma (presumably a setting of immune incompetence), BTLA expression remains high in tumor antigen-specific CD8+ T cells." (PMID 24796533, 2014). "Interrupted BTLA signaling, achieved by applying CpG oligonucleotide vaccine formulations, lead to functional recovery of melanoma-specific CD8+ T cells." (PMID 23450201, 2013). "In melanoma, BTLA expression is upregulated following immunotherapy resistance." (PMID 41471273, 2025). "Previous studies have shown that BTLA and PD-1 are co-expressed in human melanoma CD8+ T cells and hepatocellular carcinoma CD4+ T cells, and both BTLA and PD-1 can recruit SH2-containing protein tyrosine phosphatase (SHP)-1 and SHP-2 to suppress T-cell receptor signaling." (PMID 40463377, 2025). "Notably, in specific malignancies such as hepatocellular carcinoma, lung cancer, and melanoma, BTLA expression is upregulated on TILs, indicating an immune escape mechanism employed by cancer cells." (PMID 38233898, 2024).
melanoma (continued). "Therefore, Gestermann’s study showed the potential application of the combined IC therapy, including anti-BTLA Abs, in the treatment of melanoma." (PMID 38233898, 2024). "Furthermore, PD-1+TIM-3-CD8+ T cells expressing BTLA are the largest tumor-specific CD8+ T cell subset among melanoma cases that show partial dysfunction with decreased IFN-γ production compared with BTLA- T cells." (PMID 33859648, 2021). "Interestingly, targeting BTLA was able to boost proliferation and cytokine production by T lymphocytes in melanoma in vivo and in vitro." (PMID 33917094, 2021). "Although BTLA is a co-inhibitory receptor, higher frequencies and numbers of BTLA-expressing CD8+ TILs are markedly associated with positive adoptive cell therapy responses among melanoma cases." (PMID 33859648, 2021). "BTLA expression is elevated in T cells from patients with melanoma." (PMID 33859648, 2021). "Consistent with the overexpression of IRs in human melanoma, lymphoma, hepatocellular carcinoma and gastric cancer, our results show that mRNAs encoding PD-1, TIM-3, BTLA and Foxp1 are also upregulated in CD8+ T cells isolated from spleens of mice-bearing mouse 4T1 breast tumours." (PMID 31594465, 2019). "High levels of BTLA/HVEM on melanoma and gastric cancer patients correlate with poor prognosis." (PMID 29544515, 2018). "Additionally, in vitro studies using antibodies to block binding of BTLA to HVEM led to increased melanoma specific CD8+ effector T-cells proliferation and enhanced cytokines production." (PMID 28594868, 2017). "The interaction of BTLA on tumor specific T cells and HVEM on melanoma cells resulted in T cell inhibition, which could be reversed by treatment with a BTLA blocking mAb." (PMID 29211042, 2017). "HVEM is frequently expressed on melanoma cells, suggesting that the BTLA/HVEM pathway might play a role in the inhibition of efficient immune responses against cancer." (PMID 28594868, 2017). "In melanoma patients, tumor-specific T cells were found to express BTLA concurrent with HVEM." (PMID 24855562, 2014). "Melanoma-specific CD8+ T cells were shown to persistently express BTLA." (PMID 23450201, 2013). "Evaluation of melanoma data from The Cancer Genome Atlas (TCGA) revealed strong positive correlations between PDPN expression and several immune checkpoint receptors, including PD-L1, CTLA4, LAG3, TIGIT, and BTLA, with the association with PD-L1 (CD274) being the most prominent (r=0.504, p<0.001)." (PMID 41573582, 2025). "However, BTLA is not downregulated in melanoma specific CD8+ T cells and remains susceptible to functional inhibition upon HVEM ligation." (PMID 28594868, 2017). "In a co‐immunofluorescence study of HVEM expression in melanoma metastases from five patients, researchers revealed that HVEM expression was mainly observed in melanoma cells, and HVEM+ melanoma cells were found to be contiguous with BTLA+ CD8+ T cells." (PMID 40105652, 2025). "Preclinical studies demonstrate that BTLA blockade restores T cell effector function, increases IFN-γ production, and enhances tumor control in melanoma, colon, and hepatocellular carcinoma models." (PMID 41471273, 2025). "BTLA was found to be expressed at intermediate to high levels on primary CD8+/CD4 + T-cells, and its expression decreased during co-culture with melanoma cells in both T-cells populations." (PMID 38233898, 2024). "BTLA and HVEM expression was confirmed on TILs and cancer cells in several types of tumors, including melanoma, hepatocellular carcinoma, colorectal cancer, glioblastoma, and others." (PMID 38835768, 2024). "In melanoma, FAP+ CAFs induced TIGIT and BTLA expression on cytotoxic T lymphocytes via increased arginase activity." (PMID 37166418, 2023). "Previous studies have identified that BTLA can suppress the proliferation of Vδ2 T cells, while blocking the PD-1 and CTLA-4 pathways can restore T cell function and improve survival in melanoma, colon carcinoma, and ovarian carcinoma." (PMID 38077396, 2023).
melanoma (continued). "Regarding therapeutic implications, BTLA inhibition, in vitro, in combination with PD-1 and TIM-3 blockade reactivated dysfunctional melanoma antigen-specific CD8+T-cells, enhancing their proliferation and cytokine secretion." (PMID 37345056, 2023). "In melanoma, BTLA is highly expressed on tumor-specific CD8+ T cells and treatment with an anti-BTLA blocking mAb resulted in enhanced proliferative capability and cytokine production in vivo and in vitro." (PMID 33917094, 2021). "A previous examination regarding melanoma showed that BTLA+ CD8+ tumor-infiltrating lymphocytes (TILs) showed a superior response and better survival compared to BTLA- CD8+ TILs as BTLA plays a costimulatory role on activating CD8+ T-cells in melanoma." (PMID 35127742, 2021). "In melanoma patients, BTLA is expressed at high levels on Ag‐specific CD8+ T cells, and its ligand, HVEM, is expressed on melanoma cells in situ." (PMID 32508018, 2020). "While blockade of PD-1 or PD-L1 in combination with IL PV-10 therapy led to anti-tumor immunity in murine melanoma, many CD8+ T cells infiltrating tumors express other co-inhibitory molecules including Tim3, Lag3, CD160, CD244 and BTLA." (PMID 29694419, 2018). "In melanoma, BTLA participates in cross-activation (cross-talk) with herpesvirus entry mediator (HVEM), a tumor necrosis factor receptor, to induce a BTLA-dependent T cell inhibition." (PMID 29725606, 2018). "Comparably to malignant melanoma, a heterogeneous amount of PD-1, Tim-3, CTLA-4, LAG-3, and BTLA were expressed on intratumoral CD8+ T cells from 32 patients with NSCLC." (PMID 28073373, 2017). "BTLA has been shown to be expressed by naive MART-1/Melan-A CD8+ T cells and is gradually downregulated in response to vaccination with CpG-ODN in melanoma patients." (PMID 29033936, 2017). "Focusing on malignant melanoma, the triple blockade of PD1, TIM3 and BTLA leads consecutively to an increased expansion, proliferation and cytokine production of tumor-associated antigen- specific CD8+ T-cells." (PMID 28073373, 2017). "Studies that investigated coinhibitory receptor expression by NY-ESO-1-specific CD8+ T cells from advanced melanoma patients have shown that coexpression of PD-1 with TIM-3, BTLA and TIGIT indicate T cell dysfunction and exhaustion." (PMID 29033936, 2017). "For instance, it has been shown that BTLA weakens antitumor T cell activation by signaling via HVEM and BTLA inhibition augmented the propagation and antitumor activity of melanoma-specific CD8+ T cells." (PMID 27151159, 2016). "To confirm the T cell exhaustion in cancer, we first examined the expression of IRs such as PD1, TIM3, BTLA, 2B4 and LAG3 in T cells isolated from mice borne with B16F10 murine melanoma." (PMID 27447564, 2016). "CD4+TIM3+ was increased from 12% (naïve lymph nodes) to 19% (draining lymph node), other IRs phenotype such as CD4+BTLA+ (38%), CD4+2B4+ (35%), CD4+LAG3+ (27%) was also increased in draining lymph node of melanoma-bearing mice than naïve mice." (PMID 27447564, 2016). "BTLA has structural and functional similarities with CTLA-4 and PD-1, and it has been found to be highly expressed in tumor antigen-specific CD8+ T cells of melanoma patients after peptide vaccinations." (PMID 34371708, 2021). "For DSS, the high BTLA group was correlated with a higher survival rate in metastatic melanoma but not primary melanoma." (PMID 33718105, 2020). "Yet, persistent expression of BTLA has been observed in untreated melanoma patients and patients vaccinated without CpG." (PMID 29033936, 2017). "Interestingly, the co-expression of BTLA with PD-1 and TIM-3 has been shown to identify the most dysfunctional NY-ESO-1-specific CD8+ T cell population in melanoma patients." (PMID 28404974, 2017). "Notably, BTLA has been detected on spontaneous Mart-1- and NY-ESO1-specific CD8+ T cells in advanced melanoma patients." (PMID 24782858, 2014).
melanoma (continued). "Additionally, the potential value of various new inhibitory immune checkpoints (BTLA, B7 family, IDO-1, LAG-3) and costimulatory molecules (GITR, ICOS, OX40, 4-1BB, CD40, CD27) has been confirmed for melanoma treatments." (PMID 36125617, 2022). "Importantly, when using PBMC from patients with melanoma in allogeneic coculture assays, we could observe a similar tendency of the PD-1/TIM-3 and PD-1/BTLA combinations to enhance proliferation, with TIM-3 being particularly effective in both CD4 and CD8 T cells." (PMID 28588576, 2017). "Two studies on adoptive T-cell therapy in murine melanoma models described that BTLA- CD8+ T lymphocytes were not able to control tumor development in vivo, while their BTLA+ counterpart exhibited antitumor capacity, as well as greater survival and resistance to apoptosis." (PMID 37649037, 2023). "Moreover, this study highlighted that the absence of sNKG2DL in the pre-treatment serum of melanoma patients with improved OS correlated with the enrichment of few circulating T cell subsets (e.g., CD3+CD4+CD45RO+BTLA+, CD3+CD4+4-1BB+, and Th17)." (PMID 30004433, 2018).